NLRP3 (NLR family pyrin domain containing 3)
Diseases named in the same sentence as NLRP3 in open-access papers (continued):
Sharing a sentence is not in itself a finding about the gene and the disease.
type 2 diabetes (continued). "A previous study reported that the combination treatment of SGLT2i (dapagliflozin) and DPP-4i (saxagliptin) reduced the activation of the NLRP3 inflammasome and delayed DKD progression in mice with type 2 diabetes." (PMID 35129424, 2022). "ER stress-related TXNIP/NLRP3 inflammasome activation is involved in the pathophysiology of SAH, neonatal hypoxic-ischemic brain injury, type 2 diabetes, and many other diseases." (PMID 36171629, 2022). "RKIP negatively regulates NLRP1 activation and NLRP3 and NLRC4-induced inflammatory body formation and plays an important role in the pathogenesis of type 2 diabetes." (PMID 36017103, 2022). "Studies on type II diabetes mellitus, acute kidney injury, hepatocyte injury, preeclampsia, and other diseases have shown that ERS can regulate pyroptosis through the TXNIP/NLRP3 pathway." (PMID 36552271, 2022). "Among them, HIF1A may indirectly activate NLRP3, which encodes for NLRP3 inflammasomes, contributing to the inflammatory responses via IL-1β activation, which is down-regulated to a greater extent in BPD-DS in this study, and could be of key importance in the development of type 2 diabetes." (PMID 35739539, 2022). "In patients with type 2 diabetes with nephropathy, tubular P2X4R (P2X4R purinoreceptor) expression is upregulated and closely related to NLRP3 inflammasome activation and renal interstitial inflammation." (PMID 32733443, 2020). "Elevated NLRP3, ASC, IL-1β gene expression, and protein levels are observed in macrophages obtained from untreated type 2 diabetic patients." (PMID 31197747, 2019). "Although the role of NLRP3 inflammasome activation has been demonstrated, the activation of AIM2 inflammasome during type 2 diabetes is not well known." (PMID 30965677, 2019). "In addition to the role of NLRP3, AIM2 has been suggested to play a role in the pathogenesis of type 2 diabetes (T2D) as its expression levels were reported to be upregulated in patients with T2D compared to healthy controls." (PMID 41440367, 2025). "Similarly, metformin, a frontline medication for type 2 diabetes, effectively prevents the activation of the TXNIP/NLRP-3 inflammasome by mitigating ER stress and activating AMPK in macrophages." (PMID 38790650, 2024). "Cardiovascular outcome trials (CVOTs) suggest that GLP-1 RA could exert cardiorenal benefits and systemic anti-inflammatory effects in patients with type-2 diabetes through the activation of cAMP and PI3K/AkT pathways and the inhibition of NLRP-3 and MyD88." (PMID 39457081, 2024). "In a murine model of type 2 diabetes, EGCG improved high-fat-diet-induced glucose tolerance and prevented NLRP3-inflammasome-dependent inflammation suggesting that EGCG as an inhibitor of NLRP3 inflammasome activation could improve glucose tolerance." (PMID 36613784, 2022). "Similarly, specific NLRP3 inhibition with MCC950 improved inflammation and insulin sensitivity in a model of mice characterized by type 2 diabetes and dementia." (PMID 34831246, 2021). "In this study, we aimed to investigate that dietary QAE supplementation could have beneficial effects on NLRP3 inflammasome dependent hyper-inflammation and consequential renal damage by stimulation of AMPK-SIRT1 signaling in type 2 diabetes." (PMID 32471242, 2020). "Furthermore, the mechanisms for the anti-inflammatory effect of HUMSCs in inflammatory bowel disease and type 2 diabetes were through the modulation of 15-LOX-1 in macrophages 39 and suppressing NLRP3 inflammasome 17 respectively." (PMID 32210708, 2020). "NLRP3 inflammasomes have also been reported to be involved in low-grade subclinical inflammation induced by chronic exposure to high levels of free fatty acids and glucose, leading to increased apoptosis and impaired insulin secretion of β-cells in obese type 2 diabetes mellitus (T2D) patients." (PMID 31182982, 2019).
type 2 diabetes (continued). "Recent evidence has suggested that the diabetic environment (particularly type 2 diabetes) may provide the appropriate triggers to activate inflammasomes, specifically the NOD-like receptor 3 (NLRP3) inflammasome." (PMID 28348460, 2017). "One research of type 2 diabetes has shown that the maturation of caspase-1 and IL-1β, the sign of NLRP3 inflammation activation, did not required TXNIP in bone marrow-derived macrophages." (PMID 25136835, 2014). "Background/Objectives: Chronic low-grade inflammation, underpinned by persistent activation of the NLRP3 inflammasome, is a central pathological mechanism in non-communicable diseases including cardiovascular disease, type 2 diabetes, inflammatory bowel disease, and neurodegeneration." (PMID 42196944, 2026). "However, as the disease progressed, NLRP1 and NLRP3 inflammasomes failed to exert their protective effects during diabetic ketoacidosis and showed significant decline." (PMID 36993972, 2023). "Based on these backgrounds, in the current study, by establishing the mouse model of type 2 diabetes and middle cerebral artery occlusion (MCAO), we initially investigated whether inhibition of activation of NLRP3 inflammasome reduces cerebral ischemia-reperfusion injury in diabetic mice." (PMID 29853850, 2018). "Because others have suggested that danger associated molecular patterns (DAMPs) can activate inflammasomes in type 2 diabetes, we wanted to investigate whether the cytosolic HMGB1 could stimulate formation of the NLRP3 inflammasome in the retina, as well as the role of Epac1 in this activation." (PMID 28348460, 2017). "Thus, NLRP3 inflammasome has a pivotal role in DCM and could be an attractive drug target for treating type 2 diabetes." (PMID 25136835, 2014).
depression (368 papers, 2014 to 2026). "As graphically summarized, liver inflammation driven by depression was associated with intestinal barrier dysfunction and NLRP3 overactivation in liver macrophages." (PMID 41503678, 2026). "Studies have demonstrated that elevated levels of NLRP3 in patients with MI are significantly associated with an increased risk of depression." (PMID 41194915, 2025). "Adolescent mice colonized with depression-associated microbiota exhibited increased blood–brain barrier permeability, facilitating LPS translocation and NLRP3 inflammasome activation." (PMID 40977983, 2025). "The inflammation and immune responses mediated by the NLRP3 inflammasome are significant contributors to psychiatric disorders, potentially leading to behavioral changes associated with depression and cognitive impairment." (PMID 41194915, 2025). "The NLRP3 inflammasome and its activation in the hippocampus were related to depression-like behaviour induced by oestrogen deficiency in animals." (PMID 40905280, 2025). "The NLRP3 inflammasome has been implicated in the pathophysiology of depression, with its activation associated with the worsening of depressive-like behaviors." (PMID 40001468, 2025). "The activation of the NLRP3 inflammasome is intricately linked to the pathophysiology of depression." (PMID 41194915, 2025). "Several animal studies reported that depression-like behaviour in OVX animals was associated with NLRP3 inflammasome activation and enhanced IL-1β, IL-18, TLR4 and NF-κB expression in the hippocampus (Refs 153,163,164,165)." (PMID 40905280, 2025). "Similar to our data, the activation of the NLRP3 inflammasome in the hippocampus has been associated with depression-like behavior and cognitive impairment in OVX mice." (PMID 38514828, 2024). "In this study, male mice subjected to OVX surgery exhibited behavioral disturbances associated with depression, increased microglial activation, mRNA expression of NLRP3 and NF-κB, and decreased mRNA expression of sirtuin-1 in the hippocampus." (PMID 38306547, 2024). "Neuroinflammation is linked to neuropathology linked to depression, such as NLRP3 inflammasome activities and decreased hippocampal plasticity." (PMID 39337247, 2024). "These processes play an important role in transmitting extracellular stress signals, such as eATP, ultimately leading to mitochondrial damage and the activation of NLRP3, which is implicated in the stress-induced development of depression-like behavior." (PMID 38890305, 2024). "Studies indicate that excessive ROS production, causing oxidative stress, plays a key role in triggering the NLRP3 inflammasome, which is associated with various neurological disorders, such as depression." (PMID 39263574, 2024). "Specific DNA methylation pattern of NLRP3 in depressed brains was also linked to depression-associated neuroanatomical changes (cortical thickness) and neuroinflammatory processes." (PMID 39763658, 2024). "The NLRP3 inflammasome, implicated in depression risk through stress-triggered proinflammatory cytokines, also drives depression development via pyroptosis." (PMID 38892791, 2024). "Our findings showed that both doses of LUT (10 and 20 mg/kg) effectively reduced anxiety and depressive disorders and regulated the expression of genes and proteins associated with the NF-κB/NLRP3 pathway in the HC." (PMID 38911248, 2024). "Although the causes of MDD are still unclear, the NLRP3 inflammasome has been linked to the development of depression." (PMID 38855751, 2024). "The likelihood of depression is associated with increasing NLRP3 levels in myocardial infarction patients." (PMID 37763063, 2023). "Loss of TET2 activated the NLRP3/IL-1β pathway of microglia in AR mice, further accelerating the anxiety and depression-like behaviors." (PMID 38012545, 2023). "We confirmed that the Sirt1/NF-κB /NLRP3 signaling pathway was associated with luteolin treatment of depression-related dry eye disorder." (PMID 36641776, 2023).
depression (continued). "The previous reports also indicate MOOs can be absorbed and then regulate NLRP3 inflammasomes, neuronal impairment ant other dysfunction associated with depression in the brain." (PMID 36765376, 2023). "Researchers have previously shown a critical role of the NLRP3 inflammasome in the pathogenesis of depression, and there is an association between the inhibition of NLRP3 inflammasome assembly and the amelioration of depression-like behaviors in animal models." (PMID 38136199, 2023). "NLRP3 inflammasome underlies numerous debilitating disorders including depression, which elevates the expression of p65, NLRP3, ASC, cleaved IL-1β, cleaved gasdermin D, and caspase-1 and downregulates SIRT1." (PMID 37920216, 2023). "Overall, our study demonstrated the antidepressant effect of 4-MESC through the inhibition of NLRP3 inflammasome activation, suggesting the potential clinical use of 4-MESC in NLRP3 inflammasome-associated inflammatory diseases such as depression." (PMID 36909194, 2023). "Several PRRs, toll-like receptor-4 (TLR-4) and NLR family pyrin domain containing 3 (NLRP3), have been implicated in depression." (PMID 37252156, 2023). "NLRP3 inflammasome is an intracellular multiprotein complex responsible for the innate immune processes associated with infection, inflammation, and depression." (PMID 36925735, 2023). "Several studies have reported that caspase 1, IL-1β, and IL-18 are associated with depression, anxiety, and fatigue, indicating the implication of the NLRP3 inflammasome in the pathophysiology of these diseases." (PMID 36675440, 2023). "Activation of NLRP3 inflammasome was linked to the pathophysiology of different cardiovascular diseases and neurological diseases including depression by promoting the cleavage of pro-IL-1β to produce mature IL-1β." (PMID 36781714, 2023). "Evidence suggests that the etiology of depression is linked with NLRP3 inflammasome-induced inflammation." (PMID 36909194, 2023). "Growing evidence suggested that NLRP3 inflammasome was associated with depression, Alzheimer’s diseases and other diseases." (PMID 37293210, 2023). "Depression exhibited increases in IL-1β and IL-18 levels associated with activation of NLRP3 inflammasome." (PMID 35069768, 2022). "Numerous studies have linked NLRP3 inflammasome complex or pyroptosis to depression or stress-induced depressive behavior." (PMID 36558541, 2022). "In summary, our findings indicated that acacetin exerts beneficial effect in depression-associated dry eye disease, which is tightly related to gp78-mediated NLRP3 ubiquitination." (PMID 36299901, 2022). "To conclude, the present study demonstrated that acacetin prevents depression-associated dry eye disease through suppression of NLRP3 ubiquitination-mediated inflammatory response via gp78 signaling." (PMID 36299901, 2022). "In cigarette smoke-induced chronic obstructive pulmonary disease (COPD) and depression mouse models, cigarette smoke-induced glucocorticoid resistance was associated with NLRP3 inflammasome activation-induced inflammatory cascade responses." (PMID 35722622, 2022). "Numerous studies have linked chronic social defeat stress-induced depression to an NLRP3 inflammasome-dependent inflammatory response in mice, as well as the suppression of the NLRP3 inflammasome by long-term antidepressant medication treatment." (PMID 35634375, 2022). "Recent studies show that the nod-like receptor protein 3 (NLRP3) inflammasome is associated with the pathogenesis of depression-like and anxiety-like behaviors." (PMID 36267291, 2022). "Numerous studies have shown that NLRP3 activation is a key factor in the pathogenesis of depression, and neuroinflammation induced by NLRP3 activation was once thought to be an important causative factor for depression." (PMID 35722622, 2022).
depression (continued). "In fact, in an acute depression model, we also found that clomipramine can regulate NLRP3 inflammasome and pro-inflammatory processes caused by LPS administration leading to the improvement of depressive-like behaviors." (PMID 35688836, 2022). "Chronic uncontrolled stress was a major cause of depression, which leaded to the activation of caspase-1 by the NLRP3 inflammasome, followed by production of inflammatory cytokine such as IL-18 and IL-1β." (PMID 35281471, 2022). "Activation of the NLRP3 inflammasome has been found to be associated with LPS- or stress-induced depression-like behaviors in animals." (PMID 35498131, 2022). "Several damage-associated molecular patterns (DAMPs) are associated with stress and depression, especially NLRP3 and HMGB1." (PMID 35677442, 2022). "The underlying mechanism of andrographolide in improving depression by affecting autophagy and the NLRP3 inflammasome, including how andrographolide induced autophagy, remains to be elucidated." (PMID 34079796, 2021). "Current evidence demonstrates that the development of depression is associated with NLRP3-mediated pyroptosis." (PMID 33402173, 2021). "This suggests that estrogen deficiency can lead to activation of NLRP3 inflammatory bodies, which leads to hippocampal nerve inflammation, depression and anxiety." (PMID 34531719, 2021). "How does the TLR4/NLRP3 inflammasome signaling pathway induce the inflammation-associated immune response in depression?" (PMID 33505499, 2021). "In rodents, depression induced by LPS is associated with activation of NLRP3 inflammasome in the brain." (PMID 34079796, 2021). "Genetic KO of GSDMD, Casp-1, and astrocytic NOD-like receptor protein 3 (NLRP3) inflammasome in mice alleviated depression-like behaviors and inhibited the pyroptosis-associated protein expression." (PMID 34877938, 2021). "Studies suggest that estrogen deficiency results in NLRP3 inflammasome activation, leading to neuroinflammation in the hippocampus and depression and anxiety." (PMID 34733143, 2021). "One study indicated that activation of NLRP3 plays a pivotal role in the development of depression‐ and anxiety‐like behavior and in the cellular and molecular alterations associated with depression." (PMID 33609086, 2021). "The course of depression is often associated with changes in pro-inflammatory substances such as NLRP3 and IL-1β (Alcocer-Gómez, 2014)." (PMID 34526897, 2021). "Recent studies show that the Nod-like receptor protein 3 (NLRP3) inflammasome and related pathways are associated with the pathogenesis of depression." (PMID 31555091, 2019). "Although further studies are required to understand effects completely, presented results shed new lights on mechanisms of anti-inflammatory effect of melatonin in NLRP3 inflammasome activation associated with acute systemic inflammation model of depression." (PMID 31327964, 2019). "NLRP3- and caspase-1-deficient mice are resilient to depressive-like behavior, indicating that inflammation caused by activation of the NLRP3 inflammasome regulates susceptibility to depression-like behaviors." (PMID 30174579, 2018). "It has been shown that LPS- and CUMS-induced depression is associated with NLRP3 inflammasome activation in brain." (PMID 30390665, 2018). "NLRP3-dependent caspase-1 activation was reported to be significantly implicated in the progression of systemic inflammation-induced depression triggered by LPS in mice depression model." (PMID 30233319, 2018). "NLRP3 inflammasome activation is implicated in AD, Parkinson’s disease (PD), depression, anxiety, and diabetic complications, and it has been shown that inhibition of NLRP3 inflammasome activation can ameliorate these diseases." (PMID 29495433, 2018). "A previous report has demonstrated that restraint stress-induced neuroinflammation (i.e., increased activated microglia and NLRP3 expression) was associated with impaired neurogenesis, which is required for depression-like behaviors in mice." (PMID 28468634, 2017).